HGF (hepatocyte growth factor)
Diseases named in the same sentence as HGF in open-access papers (continued):
Sharing a sentence is not in itself a finding about the gene and the disease.
infectious disease (6 papers, 2005 to 2024). A disorder directly resulting from the presence and activity of a microbial, viral, or parasitic agent in humans. "Altogether, the pivotal role of the HGF-Met signaling pathway in the progression of infectious diseases, combined with our proteomic analysis, suggested a binding activity of recombinant OipA towards Met on the gastric epithelial cell surface." (PMID 39471168, 2024). "HGF is a growth factor with pleiotropic function and it is produced in response to the pro-inflammatory cytokine IL-1 in infectious diseases." (PMID 28628613, 2017). "Several lines of clinical studies demonstrated that blood and local HGF levels increased in patients with infectious diseases with septic features." (PMID 22536224, 2012). "HSPG is a sulphated glycoprotein that binds and facilitates the cytokine–receptor interaction and the conversion of promitogen HGF to the two-chain form High levels of HGF have been reported in blood during acute injuries such as infectious diseases." (PMID 18569024, 2008). "Since endogenous HGF is important for driving self-defensive system, local or systemic HGF may be useful for diagnosis of septic conditions: HGF levels significantly increase in blood or bronchoalveolar lavage fluids (BALFs) of patients during infectious diseases." (PMID 22536224, 2012).
inflammation (6 papers, 2017 to 2025). Aberrant reaction of the microcirculation characterized by movement of fluid and leukocytes from the blood into extravascular tissues. "Since the discovery and characterization of the epithelial specific growth factors keratinocyte growth factor (KGF) and HGF, their role in lung development, lung inflammation, and repair has been extensively studied." (PMID 31801626, 2019). "Furthermore, in the acute lung injury model, MSCs were found to ameliorate endothelial permeability and lung inflammation through paracrine hepatocyte growth factor or Ang-1 mRNA in MSC microvesicles." (PMID 41249792, 2025).
liver (6 papers, 2015 to 2023). "HGF overexpression is reported in GI tumors and is associated with worse outcomes." (PMID 34037097, 2021). "Alteration of the MET/ hepatocyte growth factor (HGF) pathway has been associated with more aggressive disease and poorer prognosis in different gastrointestinal neoplasms." (PMID 35834132, 2023). "Several anti-HGF and anti-c-MET monoclonal antibodies direct against extracellular combination of c-MET and HGF have been developed for the inhibition of c-MET-mediated digestive system tumor." (PMID 30360560, 2018). "In this study, we focused on the evaluation of alterations in the expression of the HGF-MET axis in ESCC, one of the spotlight targets for gastrointestinal (GI) cancer, due to its overexpression in 10 to 70% of different GI tumors (20, –22)." (PMID 34037097, 2021).
hematologic malignancies (5 papers, 2014 to 2025). "By contrast with ACR-7 and ACR-9 (hematological disorder), TNF and HGF were significantly associated with ACR-6 (serositis), TNF negatively and HGF positively." (PMID 36858042, 2023). "This brief overview outlines how upregulated c-MET expression on leukemic cells, and paracrine but also autocrine release of HGF, may create favorable conditions to the expansion of myeloid and lymphoid cells in hematological diseases." (PMID 30642077, 2019). "Although studies referring to activation of the HGF/c-MET axis in hematological diseases are relatively a few, it appears that this interaction may, directly or indirectly, favor the expansion of the leukemic clone." (PMID 30642077, 2019). "The normal c-Met/HGF pathway plays an important role in embryogenesis and wound healing, but aberrant forms of this pathway (for example, as a result of overexpression of c-Met and HGF) have frequently been observed in a variety of human solid tumors and hematologic malignancies." (PMID 24566328, 2014). "While the role of HGF/c-MET axis activation has been extensively studied in solid tumors, its potential in hematological malignancies remains underexplored." (PMID 40520181, 2025). "Finally, a better comprehension of the complex cross-talk among leukemic cells, stromal cells, and immune cells within a structured model of culture should further clarify the potential role of HGF/c-MET axis in pathogenesis and progression of hematological disease." (PMID 30642077, 2019).
retinopathy (5 papers, 2010 to 2024). "Besides, miR-200blow-expression can improve the expression of retinopathy-related proteins such asTGF-β1 and HGF, and reduce the expression of PEDF protein." (PMID 28122882, 2017). "Previously, we reported a new peptide derived from HGF, H-RN, which exhibited anti-angiogenic activity in a choroid-retinal endothelial cell line (RF/6A) and in the chick chorioallantoic membrane, as well as in a mouse model of oxygen-induced retinopathy." (PMID 23433118, 2013). "These resultssuggested that miR-200b over-expression and VEGFA low-expression canreduce the expression of retinopathy-related proteins such as TGF-β1 and HGF,while also enhance the expression of PEDF protein." (PMID 28122882, 2017). "Theseresults indicated that miR-200b over-expression and VEGFAlow-expression can reduce the mRNA expression of VEGFA and retinopathy-relatedproteins such as TGF-β1 and HGF, and enhance the expression of PEDF mRNA." (PMID 28122882, 2017). "Cell scattering induced by hepatocyte growth factor (HGF) is a precondition of RPE cell migration and proliferation involved in choroidal neovascularization and proliferative retinopathies." (PMID 23555722, 2013).
bacterial infection (3 papers, 2015 to 2023). "Hepatocytes, by producing IL-1β, IL-6, and tumor necrosis factor (TNF-α) in response to stimulation by bacterial infection, lipopolysaccharides (LPS), hepatocyte growth factor (HGF), H2O2, and TNF-α are a source of inflammatory mediators in the liver." (PMID 37153436, 2023). "pylori infection, we show for the first time,HGF also coimmunoprecipitated with c-Met, and HGF expression was significantlyupregulated in response to bacterial infection." (PMID 25658601, 2015). "Thus, our study also reveals for the first time that local levels of HGF in lung and airway rise in response to bacterial infection." (PMID 25938594, 2015).
peripheral neuropathy (3 papers, 2018 to 2021). A disorder affecting the peripheral nervous system. "Involvement of HGF/c-met pathway in axon outgrowth was further tested in the nerve crush mouse model, which is widely used in the study of peripheral neuropathy-related axon regeneration program." (PMID 33718632, 2021). "Taken together, our results indicate that HGF and c-met play important roles in Schwann cell-mediated nerve repair, and also that HGF gene transfer may provide a useful tool for treating peripheral neuropathy." (PMID 29844434, 2018). "Taken together, these results suggested that HGF/c-met pathway plays important roles in axon outgrowth by directly interacting with sensory neurons and thus HGF might be a useful tool for developing therapeutics for peripheral neuropathy." (PMID 33718632, 2021).
respiratory diseases (3 papers, 2019 to 2025). "HGF acts as a critical tissue-repair factor, and IGF1 regulates immune responses and cellular repair, with reduced levels associated with worsened outcomes in respiratory diseases including ARDS." (PMID 41200555, 2025).
benign tumors (2 papers, 2004 to 2018). "Important upstream regulators in our study, unique to benign tumours were AREG, TLR2, TGF1B, HGF, MAP3K1." (PMID 30517191, 2018).
digestive system cancer (2 papers, 2018 to 2020). A primary or metastatic malignant neoplasm involving any part of the digestive system. "So far, most of the HGF/c-Met inhibitors in digestive system cancer have been assessed in preclinical studies and phase I/II/III clinical trials." (PMID 33195182, 2020). "Numerous studies have shown the wide application of c-Met in digestive system cancers with related clinical and preclinical evidences supporting the anti-HGF/c-Met signaling pathway as a reliable treatment for HCC, gastric, pancreatic, and CRC among others." (PMID 33195182, 2020). "In the current review, the physiological and pathological mechanisms of the aberrant HGF/c-MET in digestive system cancers have been described." (PMID 30360560, 2018). "In the current review, we will discuss recent findings about inhibitors of HGF/c-MET signaling in treating digestive system cancers, and how miRNAs regulate digestive system cancers via mediating HGF/c-MET pathway." (PMID 30360560, 2018). "Multiple inhibitors of HGF/c-MET signaling have shown antitumor activity in the preclinical phase of digestive system cancers." (PMID 30360560, 2018). "The HGF/c-MET pathway is active in the development of digestive system cancers, indicating that inhibition of HGF/c-MET signaling may have therapeutic potential." (PMID 30360560, 2018). "In the future, the miRNAs-HGF/c-MET axis could serve as a potential target for digestive system cancer treatment." (PMID 30360560, 2018). "However, the clinical efficacy of some inhibitors is limited, and some novel HGF/c-MET signaling inhibitors or medication strategies are being developed for digestive system cancers." (PMID 30360560, 2018).
gastrointestinal disease (2 papers, 2009 to 2018). A disease that occurs in the gastrointestinal system, excluding the hepatobiliary system. "An association has been described between HGF serum levels and the presence of gastrointestinal disease, which is sometimes linked to ASD in subgroups of children." (PMID 30320048, 2018).
immune diseases (2 papers, 2017 to 2018). "Furthermore, MSC secretomes, including growth factors hepatocyte growth factor (HGF) or tumor-specific glycoprotein (TSG6), have been effectively utilized to treat immune diseases." (PMID 30013600, 2018).
psychiatric diseases (2 papers, 2020 to 2025). "Our results suggest that CSF APP, GDNF, and NCAM-1 levels are associated with psychiatric disorders, and that CSF HGF, S100B, and VEGF receptor 2 levels are related to psychiatric symptoms." (PMID 32439851, 2020). "In conclusion, our data suggest the involvement of state- (i.e., HGF, S100B, and VEGF receptor 2) and trait (i.e., APP, GDNF, and NCAM-1) markers associated with neuroplasticity in the pathology of psychiatric disorders." (PMID 32439851, 2020). "Finally, it cannot be determined whether the alteration of expression, processing or clearance of significant proteins (i.e., APP, GDNF, HGF, NCAM-1, S100B, and VEGF receptor 2) results in the association with psychiatric disorders." (PMID 32439851, 2020).
central nervous system disorder (1 paper, 2024). A disease involving the central nervous system. "In the context of central nervous system disorders, our approach enables the production of HGF mimetics capable of crossing the blood-brain barrier by utilizing an anti-transferrin receptor antibody as a scaffold for LG." (PMID 39108737, 2024).
CNS tumors (1 paper, 2008). "Moreover, we asked if DR5 increase by HGF in the DAOY cell line reflects a relationship between DR5 and the HGF:c-Met pathway in human embryonal CNS tumors." (PMID 18992144, 2008).
inflammatory myopathies (1 paper, 2015). "Thus, stimulation of the HGF/Met pathway may be a viable strategy for treating inflammatory myopathies, such as DMD." (PMID 25906153, 2015).
muscular disorder (1 paper, 2024). "The present work highlights the first comprehensive molecular implication of the extracellular HGF nitration/dysfunction in an age‐associated muscular disorder." (PMID 37985931, 2024).
HGF also shares sentences with these, for which no sentence is quoted: multiple myeloma (37 papers); acute myocardial infarction (22); atrial fibrillation (6); chronic hepatitis C (5); metastasis (5); primary angle-closure glaucoma (5); papillary carcinoma of the thyroid (4); rhabdomyosarcoma (4); ependymoma (3); lupus nephritis (3); Parkinson (3); Ureteral obstruction (3); acute coronary syndrome (2); allergies (2); benign breast disease (2); bronchiolitis obliterans (2); carcinoma in situ (2); central obesity (2); cholangitis (2); Chronic Myeloproliferative Neoplasms (2); chronic obstructive pulmonary disease (2); Crohn disease (2); diabetic retinopathy (2); dyslipidaemia (2); Hearing impairment (2); Hypercholesterolemia (2); hypertrophy (2); Intraventricular hemorrhage (2); kidney tumors (2); Lewis lung carcinoma (2).
A further 169 diseases each share a sentence with HGF in 2 papers or fewer.